RBPMS (RNA binding protein, mRNA processing factor)
Diseases named in the same sentence as RBPMS in open-access papers (continued):
Sharing a sentence is not in itself a finding about the gene and the disease.
lung carcinoma (2 papers, 2022). "TRHDE-AS1, the top upregulated gene following RBPMS knockout, is an antisense ncRNA downregulated in lung cancer." (PMID 35008958, 2022). "Multiple NRG1 fusion partners, including RBPMS, have been found in lung cancer patients." (PMID 36262474, 2022).
serous ovarian cancer (2 papers, 2016 to 2022). "As we observed that RBPMS was reduced at the RNA and protein levels in serous ovarian cancer patients when compared with normal ovaries, we investigated the RBPMS protein levels in cisplatin-sensitive serous ovarian cancer cells." (PMID 35008958, 2022). "We generated clustered regularly interspaced short palindromic repeats (CRISPR)-mediated RBPMS knockout vectors that were stably transfected in the high-grade serous ovarian cancer cell line, OVCAR3." (PMID 35008958, 2022).
Alzheimer disease (1 paper, 2016). A progressive, neurodegenerative disease characterized by loss of function and death of nerve cells in several areas of the brain leading to loss of cognitive function such as memory and language. "Other RBPMS partners we identified included PICALM, a clathrin adaptor with a role in Alzheimer's disease, TCF7L2, a Wnt signaling transcription factor and PATZ1, a transcriptional regulator with a role in cell death and proliferation and differentiation." (PMID 27107012, 2016).
cholangiocarcinoma (1 paper, 2021). A carcinoma that arises from the intrahepatic biliary tree (intrahepatic cholangiocarcinoma) or from the junction, or adjacent to the junction, of the right and left hepatic ducts (hilar cholangiocarcinoma). "RBPMS, an RNA-binding protein, and MET, a proto-oncogene receptor tyrosine kinase, have been identified as fusion partners in a variety of cancers with other genes and as gene fusion partners in a patient with cholangiocarcinoma." (PMID 34863095, 2021).
dementia (1 paper, 2025). Loss of intellectual abilities interfering with an individual's social and occupational functions. "In the current study, we observed increased CCasp3 expression in GCL cells, specifically in ~ 30% of RBPMS+ RGCs in AD dementia patients, but not in MCI patients compared to cognitively normal controls." (PMID 39955563, 2025).
dilated cardiomyopathy (1 paper, 2025). Cardiomyopathy which is characterized by dilation and contractile dysfunction of the left and right ventricles. "Embryonic deletion of RBPMS leads to lethality by P4 with cardiac defects including premature terminal differentiation of cardiomyocytes, while knockout in adult cardiomyocytes leads to defects in contractility and dilated cardiomyopathy." (PMID 41428739, 2025).
heart failure (1 paper, 2025). Inability of the heart to pump blood at an adequate rate to meet tissue metabolic requirements. "In heart failure and cardiomyopathy, RBPMS cooperates with RBM20 to regulate splicing of sarcomeric genes such as TTN, safeguarding contractile integrity, while DDX5 maintains calcium homeostasis through CAMK2D splicing, and loss of QKI results in profound sarcomere disarray and heart failure." (PMID 41399527, 2025).
myotonic dystrophy (1 paper, 2025). An inherited progressive disorder affecting the muscles. "The involvement of MBNL1 in the RBPMS-axis is intriguing as its dysregulation is associated with the pathology of myotonic dystrophy not only in skeletal and cardiac muscle but also potentially in gastrointestinal visceral SMCs." (PMID 41428739, 2025).
optic nerve hypoplasia (1 paper, 2022). "The RBPMS gene is also associated with optic nerve hypoplasia, hordeolum, and retinal ischemia." (PMID 35086532, 2022).
osteosarcoma (1 paper, 2022). A usually aggressive malignant bone-forming mesenchymal neoplasm, predominantly affecting adolescents and young adults. "The results showed that the expressions of MTF2 and RBPMS were upregulated in all osteosarcoma cell lines (MNNG/HOS, 143B, MG63, and WELL5) compared with the osteoblast cell line." (PMID 35734428, 2022). "The expressions of MTF2 and RBPMS in osteosarcoma tissues and normal osseous tissues were analyzed by IHC." (PMID 35734428, 2022). "MTF2 and RBPMS were both highly expressed in osteosarcoma tissues compared with normal osseous controls with p values of 0.0071 and 0.0234, respectively." (PMID 35734428, 2022). "Finally, we selected MTF2 and RBPMS for IHC validation in osteosarcoma tissues and normal osseous tissues." (PMID 35734428, 2022).
pancreatic cancer (1 paper, 2025). "Finally, NRG1 fusion partners were most commonly ATP1B1 (pancreatic cancer) or CD74 (NSCLC) in FDA-approved indications, with a mix of these as well as SLC3A2 and RBPMS being commonly observed partner genes in nonapproved indications." (PMID 41091579, 2025).
sarcoma (1 paper, 2022). A usually aggressive malignant neoplasm of the soft tissue or bone. "In order to reveal the association between the expressions of five TcoF-related genes (LMO2, MAML3, MTF2, RBPMS, and SIRT1) in the risk model and immune cell infiltration, the data on sarcoma from the TIMER database were collected." (PMID 35734428, 2022). "Mutations of each gene (LMO2, MAML3, MTF2, RBPMS, and SIRT1) in sarcoma were 6, 7, 6, 3, and 5%, respectively, with the most common changes in the mRNA expression." (PMID 35734428, 2022).
soft tissue tumors (1 paper, 2023). "To date, there are approximately 42 partner genes involving NTRK2 rearrangement, and only STRN and RBPMS are identified in the fusion with NTRK2 in adult soft tissue tumors." (PMID 37865792, 2023). "To date, only STRN and RBPMS are identified in the fusion with NTRK2 in adult soft tissue tumors." (PMID 37865792, 2023).
tauopathy (1 paper, 2025). Neurodegenerative disorders involving deposition of abnormal tau protein isoforms (tau proteins) in neurons and glial cells in the brain. "We believe the strong correlations between pS396-tau+ or Oligo-tau+ RBPMS+ RGCs and disease parameters primarily reflect the accumulation of these tauopathy forms in the retina of AD patients." (PMID 39955563, 2025).
cancer (12 papers, 2007 to 2025). A tumor composed of atypical neoplastic, often pleomorphic cells that invade other tissues. "Token together, these results indicated that the loss of RBPMS in UC promoted cancer progress through activating AP-1 transcription factors." (PMID 37704624, 2023). "Therefore, the elucidation of the biological role of the RBPMS and its splice variants represent an important research area in the cancer field." (PMID 35008958, 2022). "For example, RBPMS encodes the RNA binding protein with multiple splicing; RBPMS is one of six genes that were shared among the top up-regulated genes both in dedifferentiated carcinoma and in carcinoma with loss of 13q." (PMID 27467526, 2016). "RBPMS mRNA expression was consistently lower in various cancers than in the adjacent normal tissues." (PMID 40044952, 2025). "RBPMS inhibits malignant tumor progression by binding to and cleaving ANKRD10 mRNA, which reduces translation to ANKRD10-2 and leads to a decrease in MYC transcriptional activity." (PMID 40044952, 2025). "For example, decorin (DCN), a tumor suppressor gene (upregulated in RBPMS knockdown clones) affects the biology of various types of cancers by targeting a number of crucial signaling molecules involved in cell growth, survival, metastasis, and angiogenesis." (PMID 35008958, 2022). "The seven hub RBPs CD3EAP, POP5, NOP10, ATXN1, ZC3H12C, RBPMS, and SBDS were implicated in the progression and prognosis of many cancers." (PMID 36262474, 2022). "The first eight of the nineteen targets, PIAS3, p27, RAB10, DBF4, DUSP14, RBPMS, PDPN and CLTC, were considered to be closely associated with cancer progression after a literature review." (PMID 28120918, 2017). "Previous studies have identified the anti-tumorigenic mechanisms of RBPMS in diverse cancer types." (PMID 40044952, 2025). "Reduced RBPMS confers drug resistance to cancer cells, including bortezomib and DDP resistance." (PMID 38195842, 2024). "Among the increased proteins following RBPMS knockdown, the two ARRB members—ARRB1 and ARRB2—are deregulated in many cancer types and have been linked to the inhibition of the senescence and growth as well as the promotion of the self-renewal, progression, and invasion of cancerous cells." (PMID 35008958, 2022). "RBPMS have been proved to be involved in mRNA transport location and stability and play a key role in axon-guided smooth muscle plasticity and regulation of cancer cell proliferation and migration." (PMID 36262474, 2022). "The RNA-binding protein with multiplesplicing (RBPMS) has been shown to play important roles in axon guidance in retinalganglion cells, in the control of smooth muscle plasticity, oocyte polarity andregulation of cancer cell proliferation and migration." (PMID 26347403, 2016). "Targeting RBPMS may be a potential strategy for modulation of DDP resistance in cancers." (PMID 38195842, 2024). "Comprehensive analysis of transcriptome sequencing results pertaining to RBPMS and ANKRD10 revealed a potential interplay between RBPMS and ANKRD10-2 in influencing cancer progression, possibly through their influence on MYC target gene expression." (PMID 40044952, 2025). "Genes and AS events enrolled in the comprehensive prognostic signature included RHOT1 (ES), SH3KBP1 (AP), AGTRAP (AA), PACS2 (AP), RBPMS (AT), B3GNTL1 (AP), MOBP (AT), NPHP3 (ES), ABCC5 (RI), FKTN (ES) and FKBP8 (AA), many of which are known to play important roles in cancer biology." (PMID 32467664, 2020). "The role of the other three deregulated ncRNAs upon RBPMS knockout—LINC01036 (upregulated), LOC101927789 (downregulated), and LOC105377329 (downregulated)—have not yet been studied in cancer." (PMID 35008958, 2022).
tumor (12 papers, 2007 to 2025). "RBPMS knockout promoted a senescence phenotype and altered ncRNAs and mRNA/proteins associated with remodeling of the tumor microenvironment, cell detoxification, RNA processing, cytoskeleton network, and cell integrity, among others." (PMID 35008958, 2022). "We took advantage of our CRISPR-mediated RBPMS-knockdown clones to perform RNAseq, observing changes in the expression of several RNA transcripts, including lncRNAs and genes associated with the tumor microenvironment." (PMID 35008958, 2022). "Last, we noted that loss of RBPMS expression promoted the xenograft growth of T24 cells, whereas knockdown of c-Fos partially abrogated the effect of RBPMS and delayed the xenograft growth of tumor cells." (PMID 37704624, 2023). "In addition, knockdown of c-Fos abrogated the effect of RBPMS loss in promoting cell proliferation, confirming that the loss of RBPMS promoted tumor development through targeting c-Fos." (PMID 37704624, 2023). "We performed RNAseq in the RBPMS knockout clones and identified several downstream-RBPMS transcripts, including non-coding RNAs (ncRNAs) and protein-coding genes associated with alteration of the tumor microenvironment as well as those with oncogenic or tumor suppressor capabilities." (PMID 35008958, 2022). "In addition, we performed RNAseq and proteomics experiments in RBPMS knockout clones, finding that RBPMS regulates many non-coding RNAs (ncRNAs) and protein-coding genes associated with alteration of the tumor microenvironment, cell detoxification, RNA processing, cytoskeleton and cell integrity." (PMID 35008958, 2022). "Proliferation was upregulated by RBPMS and QK depletion, consistent with other reports that RBPMS is antiproliferative and can act as a tumor suppressor." (PMID 41428739, 2025). "We detected the RBPMS expression in the tumor tissues from DDP-sensitive and DDP-resistant OC patients." (PMID 38195842, 2024). "Pathway enrichment analysis indicated that cell cycle pathway was overexpressed in tumor harbored RBPMS deletion." (PMID 37704624, 2023). "To explore the RBPMS protein expression in the patient tumor tissues, we performed IHC analysis in a high-density tissue array." (PMID 35008958, 2022). "For example, high levels of DAB and PTGER4, two of the top upregulated genes in RBPMS clones, act as tumor suppressor genes." (PMID 36499073, 2022). "Then, we performed IHC studies to measure the RBPMS protein levels, the tumor cell proliferation rates (Ki67), and the blood vessel formation (CD31) in tissue sections of the mice tumors." (PMID 36499073, 2022). "Consistent with a role in promoting a fully differentiated state, in other cell types RBPMS has anti-proliferative tumor-suppressive activity." (PMID 31283468, 2019). "Statistical analysis of the IHC results revealed RBPMS expression to be significantly higher (*p = 0.0179) in epithelial cells of normal ovaries as compared to tumor tissue." (PMID 27166999, 2016). "Furthermore, as tumor staging advanced, a consistent downward trend in RBPMS expression was evident, suggesting a gradual decrease in its expression level with the progression of BLCA staging." (PMID 40044952, 2025). "Additionally, our investigation revealed that ANKRD10-2 knockdown mitigated the effect of RBPMS knockout on tumor cell migration." (PMID 40044952, 2025). "As expected, the RBPMS immunoreactivity was significantly higher for A2780CP20-RBPMSA (*** p < 0.0001) or A2780CP20-RBPMSC (** p < 0.01) tumor tissues compared with A2780CP20-EV tumor tissues." (PMID 36499073, 2022). "The overall findings indicate that EZH2 regulates tumor cell growth by repressing RBPMS." (PMID 30555699, 2018). "Functional study of RBPMS silenced cells validated the tumor suppressor activity of RBPMS in MM." (PMID 30555699, 2018). "Immunohistochemical intensity of RBPMS was higher in normal ovaries as compared to tumor tissue." (PMID 27166999, 2016).
tumor (continued). "These suggested that RBPMS might be a critical suppressor gene of UC tumor metastasis." (PMID 37704624, 2023). "Our findings revealed a marked decrease in RBPMS expression in BLCA tissue, with further reduction as the tumor infiltrated the muscle layer." (PMID 40044952, 2025). "Compared to normal samples, ATXN1, RBPMS, SBDS, and ZC3H12C were downregulated, and CD3EAP, NOP10, and POP5 were upregulated in UCEC tumor samples." (PMID 36262474, 2022). "CD3EAP, NOP10, and POP5 were significantly up-regulated in tumor tissue samples, while ATXN1, RBPMS, SBDS, and ZC3H12C were significantly downregulated in tumor tissue samples calculating by DESeq2 and edgeR, which were consistent with our previous results." (PMID 36262474, 2022). "Conversely, no statistically significant disparities were discerned in RBPMS expression levels across varying pathological grades, lymph node metastasis statuses, or tumor dimensions." (PMID 40044952, 2025). "There was a negative correlation between IHC scores of SH3RF2 and RBPMS staining in tumor tissues from OC patients." (PMID 38195842, 2024). "Among the 9 cis-effects, the protein abundance of RBPMS was significant lower in tumor with metastasis than non-metastasis (Wilcoxon rank-sum test, p = 0.0076)." (PMID 37704624, 2023).
cardiovascular diseases (1 paper, 2019). "Our future studies aim to understand the mechanisms of splicing regulation by RBPMS, the role of the RBPMS-regulated splicing program in controlling different aspects of SMC phenotype and the potential role of subversion of this program in cardiovascular diseases." (PMID 31283468, 2019).
RBPMS also shares sentences with these, for which no sentence is quoted: bipolar disorder (1 paper); cervical cancer (1); chronic lymphocytic thyroiditis (1); endometrial cancer (1); hypertrophic cardiomyopathy (1); mesenchymal tumors (1); myopathies (1); neurological disease (1); pituitary adenomas (1); retinal ischemia (1); retinal tumors (1).